TRBJ1-1 (T cell receptor beta joining 1-1)
Description:
J region of the variable domain of T cell receptor (TR) beta chain that participates in the antigen recognition. Alpha-beta T cell receptors are antigen specific receptors which are essential to the immune response and are present on the cell surface of T lymphocytes. Recognize peptide-major histocompatibility (MH) (pMH) complexes that are displayed by antigen presenting cells (APC), a prerequisite for efficient T cell adaptive immunity against pathogens. Binding of alpha-beta TR to pMH complex initiates TR-CD3 clustering on the cell surface and intracellular activation of LCK that phosphorylates the ITAM motifs of CD3G, CD3D, CD3E and CD247 enabling the recruitment of ZAP70. In turn ZAP70 phosphorylates LAT, which recruits numerous signaling molecules to form the LAT signalosome. The LAT signalosome propagates signal branching to three major signaling pathways, the calcium, the mitogen-activated protein kinase (MAPK) kinase and the nuclear factor NF-kappa-B (NF-kB) pathways, leading to the mobilization of transcription factors that are critical for gene expression and essential for T cell growth and differentiation. The T cell repertoire is generated in the thymus, by V-(D)-J rearrangement. This repertoire is then shaped by intrathymic selection events to generate a peripheral T cell pool of self-MH restricted, non-autoaggressive T cells. Post-thymic interaction of alpha-beta TR with the pMH complexes shapes TR structural and functional avidity.
Synonyms: TRBJ11; TCRBJ1S1
Gene: T-cell receptor joining (J) gene on chromosome 7 (142,786,880 to 142,786,927, forward strand). Ensembl gene ENSG00000282320.
Subcellular location: Cell membrane
Gene Ontology:
Cellular component: plasma membrane